INS (insulin)
Diseases named in the same sentence as INS in open-access papers (continued):
Sharing a sentence is not in itself a finding about the gene and the disease.
Cirrhosis (continued). "In order to examine tissue‐specific insulin sensitivity in CHC, only patients without cirrhosis were included to avoid the confounding effect of cirrhosis on insulin resistance." (PMID 30586166, 2019). "All antidiabetic drugs can be safely used in patients with compensated cirrhosis, while insulin is the preferred drug in decompensated Child C cirrhosis." (PMID 30413050, 2018). "Patients with cirrhosis have reduced liver insulin clearance and increased advanced glycation end-products, hypoxia, and hypoxia-inducible factors." (PMID 28352640, 2017). "The demographic, clinical and laboratory features of the participants with cirrhosis included higher levels of liver enzymes, insulin and glucose and significantly lower levels of high density lipoprotein (HDL)." (PMID 26950933, 2016). "This is because earlier studies have reported that the standardized mortality ratio from cirrhosis in diabetics was higher in patients who received insulin than in those treated by oral hypoglycemic agents." (PMID 20103955, 2010). "Three patients in human insulin mix 50 treatment discontinued from this study because of adverse events of hepatitis E, hepatic cirrhosis and angioneurotic oedema respectively." (PMID 18657196, 2008). "Furthermore, studies have shown that patients with hepatitis B–related cirrhosis exhibit impaired insulin secretion." (PMID 41462693, 2025). "Ketones produced during ketosis may protect liver cells by modulating insulin signaling pathways and enhancing mitochondrial oxygen metabolism, potentially alleviating oxidative damage in early-stage cirrhosis." (PMID 41502820, 2025). "Although SGLT2i administration in patients with decompensated cirrhosis requires careful attention, it provides good glycemic control, facilitating the avoidance of high insulin doses, and might have a positive effect on ascites." (PMID 40704640, 2025). "SGLT2i offer a biologically coherent and clinically promising adjunct to standard care for cirrhosis, particularly in patients with ascites, by coupling insulin-independent glycosuria with natriuresis, partial restoration of tubuloglomerular feedback and preferential interstitial fluid mobilization." (PMID 41465728, 2025). "However, in patients with cirrhosis, insulin titration should be approached with greater caution, accompanied by close monitoring of blood glucose levels." (PMID 40704640, 2025). "Different medical conditions, such as pregnancy, hepatic cirrhosis, and steroid therapy, may require very different ratios of mealtime to basal insulin from those experienced in standard ambulatory care." (PMID 40035222, 2025). "Through the actions of BHB, the diet improves insulin sensitivity, reduces hepatic fat deposition, and exerts anti-inflammatory and antioxidant effects, making it a promising adjunct therapy for managing alcoholic fatty liver disease and early cirrhosis." (PMID 41502820, 2025). "In HBV-related cirrhosis patients, gut microbiota dysbiosis amplifies systemic inflammation and lipid metabolic disturbances through gut-liver axis interactions, potentially impairing insulin-mediated glucose regulation." (PMID 40918255, 2025). "However, data from observational studies in patients with T2DM and advanced fibrosis or cirrhosis associated with MASH indicate that metformin lowers ALT levels and sensitizes insulin." (PMID 40141037, 2025). "Patients with advanced age, male sex, cirrhosis, oral anti-virus drug use, insulin use, and who acquired HCV coinfection had a higher HCC incidence, whether before or after propensity score matching (p < 0.0001)." (PMID 36831491, 2023). "In the context of established associations between exogenous insulin treatment and cancer, using insulin to achieve blood glucose control may balance the risk of HCC in persons with cirrhosis." (PMID 38055642, 2023).
Cirrhosis (continued). "In this study, we build upon previous findings that support the working hypothesis that the trophic effects of insulin (endogenous or exogenous) lead to an increased risk of HCC in diabetes in a cohort of persons with cirrhosis." (PMID 38055642, 2023). "However, in patients with decompensated cirrhosis, the hepatic metabolism of insulin is reduced, thereby reducing the need for insulin." (PMID 35252271, 2022). "High abundance of this metabolite is observed in impairment of insulin secretion in pancreatic beta cells and in hepatic encephalopathy conditions, and merits further investigation for its potential role as a biomarker of hepatic cirrhosis." (PMID 36056162, 2022). "With the development of cirrhosis, owing to reduced insulin extraction of liver and portal-systemic shunting, serum insulin levels will increase and insulin resistance may develop." (PMID 34118892, 2021). "Careful adjustment of the insulin dose and close monitoring of blood glucose levels may enable the effective and safe use of insulin for treating persons with cirrhosis and T2DM." (PMID 34118892, 2021). "It is observed in patients with cirrhosis that the onset of type 2 diabetes is linked to a decrease in insulin secretion rather than an increase though cirrhosis is found to be associated with increased IR leading to increased secretion." (PMID 33195350, 2020). "Indeed, our results indicate that insulin-resistant patients with cirrhosis had a higher BMI and leptin levels in comparison to insulin-sensitive ones." (PMID 32092909, 2020). "Compared with TZD nonusers, rosiglitazone and pioglitazone users, men, patients undergoing insulin treatment, using ≧3 oral antidiabetic drugs, and statin nonusers had a significantly lower risk of cirrhosis." (PMID 31960563, 2020). "One study results showed that impairment of insulin secretion, but not of insulin sensitivity, associated with severity of cirrhosis, as evaluated by CTP score, which independently predicted β-cell dysfunction." (PMID 29416767, 2018). "Serum insulin increases for patients with cirrhosis, since hepatic function disorders lead to abnormal insulin levels, which might decrease hepatic blood supply and inhibit insulin-stimulated glucose uptake." (PMID 28352640, 2017). "In particular, a peculiar genetic background of the host by conditioning the occurrence of intracellular metabolic derangements (i.e., insulin resistance) might contribute to accelerate the rate of progression to cirrhosis and eventually the occurrence of HCC." (PMID 22164334, 2011). "Serum vitamin D inversely associated with the presence of dysmetabolic conditions in our study as well as in other published reports and may play a role in both NAFLD and cirrhosis outcomes though its anti-inflammatory and insulin-sensitizing activities." (PMID 21749681, 2011). "The opposite may be the case in men where there is a gender difference in susceptibility to HCC along with altered estrogen metabolism and insulin resistance in cirrhosis." (PMID 21241523, 2011). "Patients with AIH cirrhosis prior to transplant had a slightly lower reduction in insulin requirement, maybe due to the fact that they are placed on long‐term corticosteroids to prevent disease recurrence, whereas the other indications would have discontinued at 3 months as per protocol." (PMID 40664615, 2025). "The precise mechanisms underpinning the association of diet factors and dietary patterns with incident NAFLD, cirrhosis, and liver cancer remain unclear, but could involve oxidative stress, chronic inflammation, altered gut microbiota, insulin sensitivity, and lipid peroxidation." (PMID 36558494, 2022). "Histopathological examination showed that insulin‐positive areas in islets decreased in patients with cirrhosis compared with those in patients without cirrhosis; in addition, the number of insulin‐positive cells in the pancreas was negatively associated with the pancreatic venous thickness." (PMID 35437902, 2022).
Cirrhosis (continued). "Although we cannot completely exclude the bias of cofounding by indication that physicians may choose to prescribe insulin therapy for patients with more severe cirrhosis, our study suggested that in patients with compensated liver cirrhosis, the use of insulin warranted special attention." (PMID 35252271, 2022). "Insulin requirements in persons with liver cirrhosis vary; persons with decompensated cirrhosis may need less insulin compared with persons diagnosed as having compensated cirrhosis." (PMID 34118892, 2021). "Case-control and longitudinal studies suggested that insulin may increase risk of HCC in patients with cirrhosis, while others did not confirm this harmful effect." (PMID 30413050, 2018). "The increased concentration of ketones in exhaled breath of patients with advanced cirrhosis might be dependent from increased insulin resistance and from a different metabolic response to fasting in patients with advanced cirrhosis vs those with compensated disease." (PMID 23573204, 2013). "Moreover, although metformin seems to be safer than exogenous insulin preventing cirrhosis complications, it may be difficult to maintain adequate blood glucose levels with insulin sensitizers alone." (PMID 23166628, 2012). "In particular, a peculiar genetic background of the host by conditioning the occurrence of intracellular metabolic derangements (i.e., insulin resistance) might contribute to accelerate the rate of progression to cirrhosis and eventually the occurrence of hepatocellular carcinoma (HCC) and death." (PMID 22164334, 2011). "Nevertheless, for patients with poorly controlled T2DM and decompensated cirrhosis due to MASH, insulin currently remains the primary treatment option." (PMID 40004572, 2025). "We conducted a 48-month longitudinal, retrospective cohort study of 54 patients with CTP B cirrhosis secondary to MASLD and T2DM who were initiated on SGLT2i (n=27) or insulin (n=27)." (PMID 40444235, 2025). "The results of our study are in line with the results of other studies that also reported a decrease in IR in diabetic individuals with silymarin administration as an adjunct to standard insulin therapy for T2DM or in diabetic individuals with cirrhosis." (PMID 38396727, 2024). "Accordingly, we found fasting hepatic insulin extraction, calculated as ratio of C‐peptide and insulin, to be decreased in NAFLD, and lowest in cirrhosis." (PMID 37078380, 2023). "We report a case of an obese 52-year-old woman with mixed genotype 1a/1b HCV infection with compensated cirrhosis and a 10-year history of poorly controlled T2DM on insulin therapy." (PMID 27293923, 2016). "This framework demonstrates that the strongest recommendation (HR 0.29, NNT 27–56) applies to patients without cirrhosis currently on insulin, while more modest benefits are observed with oral agent comparators or in established cirrhosis." (PMID 41388641, 2025). "GLP‐1RAs substantially reduce HCC risk in patients with T2DM, with the greatest benefits observed when used in place of insulin and in patients without cirrhosis." (PMID 41388641, 2025). "Patients with CTP B cirrhosis and T2DM receiving SGLT2i therapy experienced a significant improvement in renal, hepatic function, and glycemic control over 48 months compared to patients treated with insulin." (PMID 40444235, 2025). "The glucagon insulin ratio was decreased in NAFLD and cirrhosis compared to healthy." (PMID 37078380, 2023). "The use of GLP‐1 and SGLT‐2 inhibitors which have both been shown to cause weight loss, improve survival and potentially stabilize eGFR is preferable over insulin in our view, and we reserve insulin as back‐up therapy after initiation of these agents in those with NASH cirrhosis." (PMID 33102791, 2020).
Cirrhosis (continued). "The occurrence of memory deficits as well as reduced levels of BDNF, CREB and IRS/PI3K/Akt have been observed in a hepatic cirrhosis-induced minimal hepatic encephalopathy model, which in turn insinuates that a positive overlap between BDNF and insulin signaling does exist." (PMID 31137621, 2019). "One had abnormal liver function test results but did not have cirrhosis, while the other had hepatic cirrhosis and was previously treated with insulin." (PMID 31286966, 2019). "For example, severe NASH, cirrhosis and liver cancer have been reported to occur in non-obese mice with targeted genetic defects that enhance insulin sensitivity, or that disrupt signaling that activates NF-kB (a major pro-inflammatory factor)." (PMID 26017539, 2015). "Additionally, we previously investigated the islet insulin secretion and thickness of the pancreatic vein using the autopsy specimens of 20 and 23 individuals with and without cirrhosis, respectively." (PMID 35437902, 2022). "On the other hand, it is known that all cirrhotic patients are prone to being insulin resistant, irrespective of the etiology, because cirrhosis itself may lead to alterations in glucose metabolism." (PMID 33800465, 2021). "Our study compared the progression of cirrhotic complications between insulin users and nonusers with compensated cirrhosis and observed that insulin users seemed to have higher risks of variceal bleeding, ascites, hepatic encephalopathy, and hepatic failure than insulin nonusers." (PMID 34118892, 2021). "Insulin therapy is the treatment of choice for T2DM associated with advanced liver disease, such as Child-Pugh class C cirrhosis, and can be used in all patients with cirrhosis regardless of the severity of liver impairment, unlike the other antdiabetic drugs." (PMID 30413050, 2018). "Participants with cirrhosis had higher baseline insulin and HOMA-IR than non-cirrhotic patients in the RBV-sparing group (HOMA-IR mean difference 2.2, 95% CI 0.58–3.8, p = 0.01; insulin mean difference 52.5, 95% CI 8.5–96.4, p = 0.02)." (PMID 30884773, 2019). "For these reasons, insulin can not be considered the ideal drug to treat T2DM in NAFLD patients and its use should be reserved to patients with advanced cirrhosis who could not receive other antidiabetic drugs or patients in which T2DM is poorly controlled with oral antidiabetics." (PMID 30413050, 2018).
cardiac hypertrophy (125 papers, 2008 to 2026). "In summary, this study confirmed that Plin5 deficiency promoted lactate accumulation due to excessive NADH production from FAO in cardiomyocytes, which impaired insulin signalling and resulted in myocardial hypertrophy in leptin-deficient mice." (PMID 37667357, 2023). "ERS plays an important role in the pathogenesis of DCM by causing cardiomyocyte apoptosis, insulin resistance, calcium imbalance, myocardial hypertrophy and fibrosis." (PMID 38027018, 2023). "Animal studies have shown associations between maternal obesity and cardiac hypertrophy and dysfunction due to the effects of higher insulin levels." (PMID 35928679, 2022). "Accordingly, in this study, miRNAs that were differentially regulated in participants with more severe PTSD symptoms were also associated with insulin secretion signaling, cardiac hypertrophy and cardiac beta-adrenergic signaling canonical pathways." (PMID 34690777, 2021). "The results indicated that insulin-induced glucose uptake was decreased after myocardial hypertrophy; hypertrophy is therefore associated with myocardial insulin resistance." (PMID 31461405, 2019). "We found that pressure overload–induced cardiac hypertrophy is associated with myocardial insulin resistance, reduced fatty acid oxidation, and mitochondrial damage." (PMID 31461405, 2019). "Our results indicate that that cardiac insulin resistance caused by cardiac hypertrophy is associated with mitochondrial damage and cardiac dysfunction." (PMID 31461405, 2019). "Similarly, in rodents and rhesus monkeys, MK-8722–mediated AMPK activation drove strong insulin-independent glucose uptake in muscle, but also caused cardiac hypertrophy and glycogen build-up." (PMID 41022302, 2025). "In a model of abdominal aortic constriction-induced cardiac hypertrophy where cardiomyocytes are enlarged, cardiac-specific insulin resistance is associated with left ventricular systolic and diastolic dysfunction, even in the absence of systemic insulin resistance." (PMID 38908792, 2024). "Furthermore it has been shown that injection of insulin at day 19 of gestation in the rat leads to increased cardiac protein synthesis (a hallmark of cardiac hypertrophy)." (PMID 29635288, 2018). "Findings from this study showing increased expression of mTORC1, PI3K, and AKT suggests that prenatal T excess may underlie activation of cardiac insulin signaling pathway resulting in activation of mTORC1 culminating ultimately to cardiac hypertrophy." (PMID 27328820, 2016). "Insulin-related pathways (cluster I) are also associated with the susceptibility to cause physiologic cardiac hypertrophy by over-expression of insulin-like growth factor 1 (IGF-1) and insulin-like growth factor 1 receptor (IGF1R), via the PI3K (p110alpha) pathway." (PMID 24751578, 2014). "An experimental study on mice showed that cardiac hypertrophy, independently of glycogen storage, is caused by an enhanced insulin sensitivity and protein kinase B activation, while mutated AMPK could unbalance the phosphorylation state of cardiac troponin and myocardial contractility." (PMID 36556501, 2022). "This myokine also has important endocrine actions, such as enhancing insulin sensitivity, protecting against cardiac hypertrophy, and it also has important beneficial roles in the liver, reducing fat accumulation, inflammation and fibrosis." (PMID 40507111, 2025). "Insulin signaling plays a crucial role in the regulation of physiological cardiac hypertrophy through a series of intricate molecular mechanisms." (PMID 39125938, 2024). "This review investigates the insulin–heart axis, focusing on insulin’s multifaceted influence on cardiac function, from metabolic regulation to the development of physiological cardiac hypertrophy." (PMID 39125938, 2024).